EGR3 (early growth response 3)
Diseases named in the same sentence as EGR3 in open-access papers (continued):
Sharing a sentence is not in itself a finding about the gene and the disease.
schizophrenia (continued). "Moreover, pedigree and case-control analyses in a study utilizing a Japanese sample found that EGR3 was significantly associated with schizophrenia; this result was also replicated in a Korean population study." (PMID 22276163, 2012). "Hence, much work is still to be done to identify the contribution of EGR3 to the involvement in genetic risk for schizophrenia." (PMID 22276163, 2012). "In addition to being downstream and upstream of susceptibility genes, EGR3 has been linked to a number of miRNAs that have been associated with schizophrenia." (PMID 22276163, 2012). "Considering the core position of EGR3 in the CN signaling pathway, and its interaction with a number of candidate risk factors implicated with schizophrenia, it strongly warrants investigation of the molecular basis of EGR3 in relationship to the pathogenesis of schizophrenia." (PMID 22276163, 2012). "In addition to EGR3's essential function for neuron activity, EGR3 also interacts with a number of factors implicated in the risk and pathogenesis of schizophrenia." (PMID 22276163, 2012). "The results of our meta-analysis suggest that EGR3 may have a small, but significant effect in the susceptibility to the development of schizophrenia, at least in the tested East Asian populations." (PMID 22276163, 2012). "EGR3 has been reported to be associated with schizophrenia in both case-control and family-based studies and its expression has been shown to be decreased in schizophrenia patients." (PMID 20156358, 2010). "Based on the central role of EGR3 in these critical processes, we hypothesized that genes regulated downstream of EGR3 will contribute to risk for schizophrenia and other neuropsychiatric disorders that are characterized by abnormalities in cognition, memory, and synaptic function." (PMID 35941129, 2022). "In addition, Egr3 has been associated with risk for schizophrenia in Japanese, Korean, Han Chinese populations, and populations of European Descent, and Egr3 expression is decreased in the brains of patients with schizophrenia, compared with controls." (PMID 29867393, 2018). "Functional polymorphisms in Egr3 and its regulatory targets such as Arc may prove useful biomarkers for sensitivity to the negative impacts of sleepiness on cognition, as they have for symptoms of schizophrenia risk." (PMID 30158860, 2018). "Although the statistically significant findings supporting an association between EGR3 and psychiatric illness have been in schizophrenia, research has increasingly demonstrated that the molecular and genetic processes underlying BD and schizophrenia are highly coincident." (PMID 27163206, 2016). "To test our hypothesis that ARC, a direct gene target of EGR3, is also a schizophrenia risk gene, we genotyped rs35900184 in a CH population of 491 cases and 491 controls in which EGR3 had previously demonstrated association with schizophrenia." (PMID 26474411, 2015). "Our independent replication of the association of SNP rs35201266 with schizophrenia, in consideration with similar studies, reduces the likelihood that the association we observed was a false-positive and suggests that EGR3 gene may indeed be a risk factor for schizophrenia." (PMID 22276163, 2012). "EGR3 may play a very important role in the pathological mechanism underlying schizophrenia." (PMID 22276163, 2012). "Other interesting genes, EGR3 and EGR4, both upregulated in response to neuronal activity, are central to schizophrenia risk pathways." (PMID 40719049, 2025). "Early growth response 3 (EGR3) and some miRNAs play a modulatory role in the schizophrenia regulatory neuronal network." (PMID 35916975, 2022). "Our findings show that EGR3 is critical for the expression of genes that are mis-expressed in schizophrenia and reveal a novel requirement for EGR3 in the expression of genes involved in activity-induced DNA damage response." (PMID 35941129, 2022).
schizophrenia (continued). "This indicates that Egr3 is required for function of a receptor at the center of one of the leading models of schizophrenia pathogenesis, the NMDA (GRIN) receptor hypofunction model of schizophrenia." (PMID 35941129, 2022). "EGR3 has been identified as such a master regulator in neuropsychiatric illnesses of schizophrenia, bipolar disorder and, most recently, Alzheimer’s dementia." (PMID 35941129, 2022). "In summary, we report activity-dependent gene expression changes in the hippocampus of Egr3−/− mice, previously shown to exhibit schizophrenia-like behavioral abnormalities and memory deficits." (PMID 35941129, 2022). "We injected the early growth response gene (EGR3) into the bilateral hippocampus to build a schizophrenia rat model." (PMID 33192626, 2020). "In a study by Ma, schizophrenia rat models were developed by injecting lentivirus particles that carried the EGR3 gene into the hippocampus and dentate gyrus of the rat brains." (PMID 33192626, 2020). "EGR3 has been associated with risk for schizophrenia in Japanese, Korean, Han Chinese, and US populations of European descent and levels of EGR3 are reduced in the brains of schizophrenia patients." (PMID 29867393, 2018). "Our studies revealed that Egr3−/− mice display behavioral abnormalities consistent with animal models of schizophrenia." (PMID 29520222, 2018). "High levels of EGR3 positively correlate with levels of proinflammatory cytokines in peripheral monocytes of schizophrenia patients." (PMID 29520222, 2018). "EGR3 is a member of the Egr family of immediate early gene zinc finger transcription factors, and is activated downstream of numerous schizophrenia candidate proteins, including NRG1, NMDAR and CN." (PMID 29520222, 2018). "Egr3−/− mice exhibit schizophrenia-like behavioral phenotypes, including failure to habituate to novel social stimuli and acoustic stimuli." (PMID 30158860, 2018). "A recent review highlighted that EGR3 was among 20 genes of interest for schizophrenia, map to the 8p locus (Tabarés-Seisdedos and Rubenstein, 2009)." (PMID 29520222, 2018). "It was also reported that decreased EGR3 mRNA levels were observed in postmortem dorsolateral prefrontal cortex samples of schizophrenia patients compared with controls." (PMID 29520222, 2018). "Investigations published by our group revealed that Egr3−/− mice display schizophrenia-like behavioral abnormalities, including locomotor hyperactivity that is reversed by antipsychotic treatment." (PMID 29520222, 2018). "The regulatory relationships with schizophrenia-associated EGRs (EGR1 and EGR3) suggest a role for NAB2 in neuropsychiatric illness." (PMID 29520222, 2018). "An interesting candidate that unites genetic findings in schizophrenia is Early Growth Response 3 (EGR3)." (PMID 26738766, 2016). "In the EU group EGR3 SNP rs1877670 showed a trend toward association (p = 0.07), and the ARC SNP rs35900184 revealed a significant association with the schizophrenia diagnosis (p = 0.02)." (PMID 26474411, 2015). "In the EU group of 386 schizophrenia cases and 150 controls EGR3 SNP rs1877670 and ARC SNP rs35900184 showed significant associations (p = 0.0078 and p = 0.0275, respectively)." (PMID 26474411, 2015). "To identify variations within the EGR3 and ARC loci that have a high likelihood for association with schizophrenia risk in two different racial groups, we used a two-step approach." (PMID 26474411, 2015). "Accordingly, variations in the immediate early gene EGR3, and its target ARC, should influence schizophrenia susceptibility." (PMID 26474411, 2015). "The early growth response 3 (EGR3) gene located in chromosome 8p21.3 was also found to be involved in the etiology of schizophrenia." (PMID 22276163, 2012). "Expression of EGR3 was also reported to be down-regulated in the dorsolateral prefrontal cortex of patients with schizophrenia." (PMID 22276163, 2012).
schizophrenia (continued). "We genotyped four SNPs (average interval ∼2.3 kb) in the chromosome region of EGR3 in 470 Chinese schizophrenia patients and 480 control subjects." (PMID 22276163, 2012). "Further exploration regarding functional relationship between miR-15 family and EGR3 gene involved in the pathogenesis of schizophrenia will be worthwhile." (PMID 22276163, 2012). "Induction of EGR3 by BDNF enables EGR3 to control the expression of Gamma-aminobutyric acid receptor (GABAR), which is also a candidate risk gene for the schizophrenia." (PMID 22276163, 2012). "EGR3 is also a target gene for Brain-derived neurotrophic factor (BDNF) and Neuregulin 1 (NRG1), both of which are schizophrenia susceptibility genes." (PMID 22276163, 2012). "To investigate the genetic role of EGR3 in Chinese patients, we genotyped four SNPs (average interval ∼2.3 kb) in the chromosome region of EGR3 in 470 Chinese schizophrenia patients and 480 healthy control subjects." (PMID 22276163, 2012). "We summarized the findings of several GWASs that have detected associations with genetic variants in the vicinity of chromosome 8p, the same region that contains EGR3, and schizophrenia." (PMID 22276163, 2012). "We revealed some schizophrenia related miRNA-TF regulatory modules and constructed a converged miRNA-TF regulatory network in which EGR3 and hsa-miR-195 served as core regulators." (PMID 20156358, 2010). "By combining miRNA-TF network analysis and literature survey, we proposed a pathway model highlighting EGR3 and miRNAs involving in the signal transduction and regulatory pathways in schizophrenia." (PMID 20156358, 2010). "Moreover, the downregulation of EGR1, EGR2, and EGR3 transcripts was reported in the postmortem brains of patients with schizophrenia." (PMID 39518903, 2024). "The immediate early gene transcription factor early growth response 3 (EGR3) has emerged as such a master regulator of differentially expressed genes (DEGs) in multiple neuropsychiatric disorders including schizophrenia, bipolar disorder, and most recently Alzheimer’s dementia." (PMID 35941129, 2022). "As an immediate early gene, EGR3 expression is induced in response to neuronal activity in a manner dependent upon GRIN receptor function and calcium signaling, processes implicated in schizophrenia." (PMID 35941129, 2022). "Next, we tested the original hypothesis for our study, that EGR3 regulates genes that play a role a role in schizophrenia." (PMID 35941129, 2022). "In our study, we observed upregulation of EGR3 in schizophrenia patients compared to controls." (PMID 31959813, 2020). "This phenotype may be explained, at least in part, but the reduced level of serotonin 2A receptors found in the frontal cortex of Egr3−/− mice, a feature also seen in the brains of patients with schizophrenia." (PMID 29520222, 2018). "Egr3−/− mice also display a marked resistance to the sedating effect of clozapine, and other second-generation antipsychotics, which parallels the resistance that schizophrenia patients show to the side-effects of these medications." (PMID 29520222, 2018). "Dysfunction of any of the proteins in this pathway would reduce the normal activation of a key transcription factor, early growth response 3 (EGR3), an immediate early gene that is both associated with schizophrenia in humans, and expressed at reduced levels in patients’ brains." (PMID 29520222, 2018). "Genome-wide association studies from the PGC schizophrenia studies suggest that none of the SNPs in the region including EGR3 showed a significant association." (PMID 29520222, 2018). "This led us to hypothesize that other genes in this pathway that shared the characteristics of regulating memory and hippocampal LTD, such as the EGR3 target gene ARC, should also be candidates for a role in schizophrenia susceptibility." (PMID 29520222, 2018). "To answer whether Egr3 may play a role in schizophrenia, we investigated the behavior and physiology of Egr3-deficient (−/−) mice." (PMID 29520222, 2018).
schizophrenia (continued). "Thus, the modulation of both 5HT2a signaling and VEP magnitude in wakefulness as a function of Egr3 genotype suggest a potential role for Egr3 as a genetic regulator of abnormalities in experience-dependent processes in schizophrenia." (PMID 30158860, 2018). "We therefore carried out the current studies to test the hypothesis that EGR3 and ARC are schizophrenia risk associated genes." (PMID 26474411, 2015). "If so, then dysfunction of the gene activity-regulated cytoskeleton-associated protein (ARC), which is a downstream target of EGR3 and is similarly required for memory formation and hippocampal LTD in mice, may also confer risk for schizophrenia." (PMID 26474411, 2015). "Therefore, EGR3 is a compelling candidate gene for schizophrenia from functional and positional perspective." (PMID 22276163, 2012). "Hence, we performed a study to further explore the relationship between EGR3 and schizophrenia in a case-control sample of Chinese." (PMID 22276163, 2012). "EGR3−/− mice were reported to display heightened reactivity to stress and novelty, abnormalities in social interactions, and deficits in synaptic plasticity, which model the cognitive deficits of schizophrenia." (PMID 22276163, 2012). "Reduced expression of EGR3 has also been observed in patients with schizophrenia." (PMID 22276163, 2012). "Mice lacking EGR3 and schizophrenia patients display a similar decreased susceptibility to the side effects of antipsychotic medications." (PMID 20156358, 2010). "Moreover, EGR3 is a downstream gene of many signaling pathways including pathways triggered by NGF, BDNF and NRG1, of which BDNF and NRG1 are schizophrenia susceptibility genes." (PMID 20156358, 2010). "We revealed that EGR3 and hsa-miR-195 are critical in the schizophrenia regulatory network." (PMID 20156358, 2010). "Hence, studies on sensory processing in Egr3−/− mice may yield insights into the influence of arousal mechanisms and deficits in experience-dependent plastic processes in schizophrenia." (PMID 30158860, 2018). "EGR3 binds to NAB2 to co-regulate expression of target genes, and is involved in co-regulatory feedback relationships with EGR1, as well EGR1, EGR2 and EGR3 can regulate NAB2 expression, demonstrating a functional interaction of both of these schizophrenia associated genes in the proposed pathway." (PMID 29520222, 2018). "These roles that Egr3 plays in memory, synaptic plasticity, and behavior, and the response to antipsychotics that mimics that of patients, suggest that abnormal function of EGR3 in humans may contribute to schizophrenia pathogenesis or symptomatology." (PMID 29520222, 2018). "Early growth response 3 (Egr3) is an immediate early gene (IEG) that is regulated downstream of a cascade of genes associated with risk for psychiatric disorders, and dysfunction of Egr3 itself has been implicated in schizophrenia, bipolar disorder, and depression." (PMID 29867393, 2018). "In addition, significant associations between SNPs in EGR3 and schizophrenia have not been reported in populations of European or African descent." (PMID 26474411, 2015). "In addition to the genetics findings, post mortem studies have reported reduced EGR3 mRNA levels in schizophrenia patients’ brains, and a biomedical informatics study identified EGR3 as the central gene in a network of microRNAs and transcription factors implicated in schizophrenia pathogenesis." (PMID 26474411, 2015). "Although our study did not demonstrate association between schizophrenia and EGR3 SNPs rs1877670 or rs1996147 in the AA cohort, the limited number of available AA DNA samples led to the study being insufficiently powered to detect variations of low effect size." (PMID 26474411, 2015).
schizophrenia (continued). "The identification of EGR3-dependent genes in the mouse hippocampus may help to explain findings indicating that EGR3 may be a master regulator of genes differentially expressed in neuropsychiatric illnesses ranging from schizophrenia and bipolar disorder to Alzheimer’s dementia." (PMID 35941129, 2022). "The genes HGF, PRRT2, EGR1, EGR3, C11orf87, TLR3 and PLEKHH2 have been reported in either genetic analysis or gene expression analysis of schizophrenia, and were all upregulated in fibroblasts from patients in our study." (PMID 31959813, 2020). "As a critical mediator of numerous biological processes disrupted in schizophrenia, such as growth factor signaling, myelination, vascularization, immune function, memory formation and synaptic plasticity, insufficient activation of EGR3 may result in neuropathology that gives rise to schizophrenia." (PMID 29520222, 2018). "Multiple studies have now demonstrated a link between EGR3, 5-HT2A receptor expression, and schizophrenia-like behaviors in transgenic animals." (PMID 26738766, 2016). "EGR3 also resides in a copy number variation (CNV)-containing region of the chromosome, and CNVs have demonstrated a high correlation with schizophrenia and other psychiatric illnesses." (PMID 26474411, 2015). "Since EGR3 is a core gene in our miRNA-mediated schizophrenia network, this provides another link for ESR1 to schizophrenia." (PMID 20156358, 2010). "EGR3 interacts in regulatory feedback loops with other EGR-family genes in the immune system, including EGR1, EGR2, EGR4 and NAB2, each of which maps to GWAS loci for schizophrenia." (PMID 35941129, 2022). "In addition, EGR3 was identified in a screen for genes that are expressed at reduced levels in the brains of schizophrenia patients that do not smoke tobacco, and are normalized to control levels in patients that smoke." (PMID 29520222, 2018).